TBC1D3K (TBC1 domain family member 3K)
Description:
Acts as a GTPase activating protein for RAB5. Does not act on RAB4 or RAB11 (By similarity).
Gene: Protein-coding gene on chromosome 17 (37,924,415 to 37,935,371, forward strand). Ensembl gene ENSG00000273513.
Subcellular location: Cell membrane
Subcellular location (Human Protein Atlas): Vesicles
Gene Ontology:
Molecular function: GTPase activator activity
Cellular component: plasma membrane; endosome; membrane
Homologues: Orthologues: chimpanzee TBC1D3B (96% identical). Paralogues in human: TBC1D3 (99% identical), TBC1D3C (99% identical), TBC1D3E (99% identical), TBC1D3F (99% identical), TBC1D3D (99% identical), TBC1D3G (99% identical), TBC1D3I (99% identical), TBC1D3H (99% identical), TBC1D3L (99% identical), TBC1D3B (99% identical), TBC1D26 (30% identical), USP6NL (29% identical), and 33 more.